TREM1 (triggering receptor expressed on myeloid cells 1)
Diseases named in the same sentence as TREM1 in open-access papers (continued):
Sharing a sentence is not in itself a finding about the gene and the disease.
type 2 diabetes (2 papers, 2025). "In this prospective cohort, our data further confirms that TREM-1 is negatively correlated with FMD in patients with type 2 diabetes." (PMID 41451290, 2025).
Ureteral obstruction (2 papers, 2019 to 2021). Obstruction of the flow of urine through the ureter. "A recent study in a mouse model of experimental unilateral ureteral obstruction found loss of TREM-1 attenuated activation of M1 macrophages, resulting in reduced renal pathology." (PMID 31509552, 2019).
AA amyloidosis (1 paper, 2021). Secondary amyloidosis is a form of amyloidosis, that complicates chronic inflammatory disorders (mainly rheumatoid arthritis) and is characterized by the aggregation and deposition of amyloid fibrils composed of serum amyloid A protein, an acute phase reactant. "Two genes within those characterizing the affected cats were reported in the literature as related to AA amyloidosis: TREM1 and TNFRSF1A." (PMID 33863921, 2021).
abscess (1 paper, 2018). An inflammatory process characterized by the accumulation of pus within a newly formed tissue cavity which is the result of a bacterial, fungal, or parasitic infection or the presence of a foreign body. "GO analysis with the unique differential promoters involved in Munro’s abscess formation revealed neutrophil and leukocyte chemotaxis as the highest enriched biological processes which include genes like HRH1, PDE4D, CCL25, AIF1, ADAM10, FFAR2, IL1B and TREM1." (PMID 30092825, 2018).
acute cholangitis (1 paper, 2020). Cholangitis that is both sudden in onset and of a relatively short duration. "In patients with acute cholangitis, it has been found that upon progression of the disease, the transcripts of TREM-1 gene decrease." (PMID 32508526, 2020).
Acute hepatitis (1 paper, 2023). Acute hepatic injury resulting from inflammation typically accompanied by increased serum alanine transaminase activity. "In addition, BIL-CRISPR–mediated editing of Trem1 — a well-characterized amplifier of inflammation expressed on KCs — almost completely abolished concanavalin-induced (ConA-induced) acute hepatitis and prevented the rapid loss of resident KCs in ConA-treated mice." (PMID 36821387, 2023).
acute respiratory distress syndrome (1 paper, 2011). Progressive and life-threatening pulmonary distress in the absence of an underlying pulmonary condition, usually following major trauma or surgery. "• Alveolar soluble triggering receptor expressed on myeloid cells 1 (sTREM-1) is useful in diagnosing lung infections in the context of acute respiratory distress syndrome." (PMID 21294874, 2011).
Adamantinomatous Craniopharyngioma (1 paper, 2016). A craniopharyngioma consisting of broad strands, cords and bridges of a multistratified squamous epithelium with peripheral palisading of nuclei. "Herein, we examined the expression and localization of β-catenin, BRAF p.V600E (V600E), and triggering receptor expressed on myeloid cells-1 (TREM-1) in 58 samples including 20 pCPs, 26 adamantinomatous craniopharyngiomas (aCP), and 12 RCCs." (PMID 27409178, 2016).
adenoma (1 paper, 2017). A neoplasm arising from the epithelium. "In Trem1+/+ and also Trem1−/− mice, most tumors represented advanced adenomas." (PMID 29093489, 2017).
allergic bronchopulmonary aspergillosis (1 paper, 2021). Allergic bronchopulmonary aspergillosis (ABPA) is a rare immunologic pulmonary disorder caused by hypersensitivity to Aspergillus fumigatus, clinically manifesting with poorly controlled asthma and recurrent pulmonary infiltrates. "Increased TREM1 expression is observed in monocyte-derived macrophages from patients with chronic pulmonary aspergillosis, while reduced TREM1 expression is observed in individuals suffering from allergic bronchopulmonary aspergillosis." (PMID 33525982, 2021).
ankylosing spondylitis (1 paper, 2009). An autoimmune chronic inflammatory disorder characterized by inflammation in the vertebral joints of the spine and sacroiliac joints. "Triggering receptor expressed on myeloid cells (TREM)-1 has also previously been implicated in the pathogenesis of ankylosing spondylitis." (PMID 19900269, 2009).
aortic valve stenosis (1 paper, 2022). Aortic valve stenosis (AVS) is a condition characterized by narrowing of the heart's aortic valve opening. "Furthermore, TREM1 signaling was one of the top five enriched pathways based on peripheral blood gene analysis from patients with aortic valve stenosis." (PMID 35722091, 2022).
aspergillosis (1 paper, 2021). Aspergillosis is an infection, growth, or allergic response caused by the Aspergillus fungus. "In this sense, our study showed that, compared to WT mice, immunosuppressed Trem1−/- mice were more susceptible to aspergillosis." (PMID 33525982, 2021). "As expected, immunosuppression resulted in enhanced susceptibility in both genetic backgrounds, however, immunosuppressed Trem1−/− mice showed earlier and more evident symptoms typical of the in vivo mouse model of aspergillosis such as hunching, head tilting, and circling compared to Trem1+/+ mice." (PMID 33525982, 2021).
basal cell carcinoma (1 paper, 2024). A carcinoma involving the basal cells. "TREM1 myeloid-derived cytokines IL1 and OSM induce basal-to-inflammatory transition in vitro and in vivo through NF-κB, lowering sensitivity of patient basal cell carcinoma explant tumors to Smoothened inhibitor treatment." (PMID 39289380, 2024).
biliary tract cancer (1 paper, 2024). "Lastly, to contextualize the role of TREM1 myeloid signature in other solid tumors in relation to therapy response, we evaluated scRNA-Seq datasets of human metastatic urothelial cancer and human biliary tract cancer undergone immune checkpoint blockade therapy, with a focus on myeloid populations." (PMID 39289380, 2024).
breast invasive carcinoma (1 paper, 2025). "The PFS analysis revealed that TREM1 acted as a risk factor for patients with breast invasive carcinoma (BRCA), KIRC and LGG and a protective factor for patients with lymphoid neoplasm diffuse large B-cell lymphoma (DLBC)." (PMID 39744496, 2025).
cervicitis (1 paper, 2016). An acute or chronic inflammatory process that affects the cervix. "In order to examine the significance of TREM-1 expression in distinguishing normal SE from metaplastic SE, we examined TREM-1 expression in various tissues, including cervical SE and metaplastic SE from cervicitis." (PMID 27409178, 2016).
coinfection (1 paper, 2019). The simultaneous infection of a host by multiple pathogen species. "This indicates that TREM1 signaling can augment virus driven liver pathology as we propose for patients with HIV and HCV coinfection." (PMID 31260499, 2019).
corneal infection (1 paper, 2024). A viral or bacterial infectious process affecting the cornea. "The current study has unveiled a significant upregulation in TREM1 in both the cornea and conjunctiva of the corneal infection patient." (PMID 38694515, 2024).
coronary atherosclerosis (1 paper, 2017). Atherosclerosis of the coronary vasculature. "Another SNP located also within the TREM-1 gene (rs4711668) has been associated with severe coronary atherosclerosis in a Russian population." (PMID 28771614, 2017). "Indeed, the polymorphism rs4711668, which is located within the TREM-1 gene has been associated with severe coronary atherosclerosis in a Russian population." (PMID 28771614, 2017).
cutaneous leishmaniasis (1 paper, 2021). Leishmaniasis affecting the skin. "Our aim is to identify whether the TREM1 variant rs2234237 A/T (Thr25Ser) is associated with the disease development of cutaneous leishmaniasis (CL) in Leishmania guyanensis-infected individuals." (PMID 33924130, 2021).
cystic fibrosis (1 paper, 2008). Autosomal recessive disorder caused by pathogenic variants in the CFTR gene (cystic fibrosis transmembrane conductance regulator), which encodes a chloride and bicarbonate channel expressed in epithelial cells, and follow the diagnosis criteria. "On the basis of these findings, we conclude that polymicrobial lung infections in patients who suffer from cystic fibrosis are due at least partly to a deficiency in their innate immune responses, and that impaired TREM-1 expression plays a role in this deficiency." (PMID 18628981, 2008). "We conclude that down-regulation of TREM-1 expression in cystic fibrosis patients is at least partly responsible for the endotoxin tolerance state in which their monocytes are locked." (PMID 18628981, 2008).
diabetic nephropathy (1 paper, 2019). "In biopsies of renal tissue with human diabetic nephropathy, with the progress of DN, CD68, M1 macrophages (iNOS), M2 macrophages (MR) and TREM-1 were mainly detected in interstitium and significantly increased compared with the control group." (PMID 31509552, 2019).
eosinophilia (1 paper, 2023). "Whether or not the patient was on definitive treatment (with a biologic or steroid-sparing immunosuppressant) did not appear to have major impact on anti-TREM1 and anti-EPX serology, and neither did presence/absence of current blood eosinophilia." (PMID 37334358, 2023).
esophageal carcinomas (1 paper, 2024). A primary or metastatic malignant neoplasm involving the esophagus. "We performed gene set enrichment and SODEGIR analyses to identify enrichment in TREM1, PGC, INHBA, and AGR, all of which are involved in cancer-related pathways and associated with patient prognosis in esophageal carcinomas and premalignant Barrett’s epithelium." (PMID 39123475, 2024).
gastroparesis (1 paper, 2019). Paralysis of the muscles of the stomach wall resulting in delayed emptying of the gastric contents into the small intestine. "In contrast, PDGF BB and TREM1 were the most significant predicted upstream regulators of the idiopathic gastroparesis groups." (PMID 31221130, 2019).
glaucoma (1 paper, 2020). Increased pressure in the eyeball due to obstruction of the outflow of aqueous humor. "Determining the function of TREM1 signalling in glaucoma is likely to uncover more specific mechanisms of damage by elevated IOP and protection by radiation therapy." (PMID 32450896, 2020). "TREM1 signalling may be a critical factor in controlling microglial activation in glaucoma and needs to be tested further." (PMID 32450896, 2020).
Glomerular sclerosis (1 paper, 2021). Accumulation of scar tissue within the glomerulus. "Furthermore, in CKD patients, urinary TREM-1/TREM-2 ratio correlated with score of glomerular sclerosis (rs= −0.436, p < .001) and score of TIF (rs= −0.628, p < .001)." (PMID 34176389, 2021).
glomerulonephritis (1 paper, 2016). A renal disorder characterized by damage in the glomeruli. "TREM-1 blockade with an inhibitory peptide, LP17, inhibited proteinuria and renal disease as measured by glomerulonephritis class, severity of tubulointerstitial disease, crescent formation, and inflammatory cell infiltrates." (PMID 27083877, 2016). "TREM-1 eluted from the kidneys of anti-GBM-diseased mice with varying disease severity correlated with tubulointerstitial disease (TI) score, glomerulonephritis (GN) score, and serum creatinine levels." (PMID 27083877, 2016).
heart failure (1 paper, 2018). Inability of the heart to pump blood at an adequate rate to meet tissue metabolic requirements. "Also, inhibition of TREM-1 in its downstream signaling protects against heart failure, post-AMI." (PMID 30205488, 2018).
hemorrhagic stroke (1 paper, 2024). A stroke caused by a bleed on the brain. "To date, several preclinical studies have reported the role and potential mechanisms of TREM1 in hemorrhagic stroke." (PMID 38385036, 2024). "In this review, we have systematically outlined the structure and function of TREM1/2, as well as their roles and potential mechanisms in hemorrhagic stroke, with the aim of providing new insights into the development of potential therapeutic options." (PMID 38385036, 2024). "This review comprehensively summarizes the structure and function of TREM1/2, as well as their roles and potential mechanisms in hemorrhagic stroke, with the aim of providing guidance for the development of targeted therapeutic strategies in the future." (PMID 38385036, 2024). "Current evidence suggests that TREM1 mediates EBI after hemorrhagic stroke by engaging neuroinflammation and BBB destruction." (PMID 38385036, 2024). "The roles of TREM1/2 in hemorrhagic stroke need further validation in higher primates and clinical studies." (PMID 38385036, 2024). "In summary, current evidence suggests that the TREM1 signaling pathway is involved in the inflammatory response and BBB disruption in hemorrhagic stroke and ultimately exacerbates secondary brain damage." (PMID 38385036, 2024).
Huntington disease (1 paper, 2022). Huntington disease (HD) is a rare neurodegenerative disorder of the central nervous system characterized by unwanted choreatic movements, behavioral and psychiatric disturbances and dementia. "Neuroinflammation signaling was predicted to be the foremost canonical pathway of α-synuclein followed by Huntington’s disease, TREM1 signaling, phagosome maturation, and sirtuin signaling pathways." (PMID 36523604, 2022). "Here, we remind that the expression analysis of the α-synuclein NCBI gene dataset had predicted neuroinflammation, Huntington’s disease, TREM1, phagosome maturation, and sirtuin signaling as the major canonical pathways of α-synuclein." (PMID 36523604, 2022). "IPA of the α-synuclein NCBI gene dataset revealed neuroinflammation, Huntington’s disease, TREM1, phagosome maturation, and sirtuin signaling as the key canonical signaling pathways." (PMID 36523604, 2022). "Huntington’s disease displayed a relatively higher extent of overlapping with phagosome maturation signaling molecules while exhibiting the least overlapping with TREM1 signaling molecules." (PMID 36523604, 2022).
hydronephrosis (1 paper, 2013). Collection of urine in the renal pelvis that results in dilatation of the renal pelvis and calyces. "In renal tissue from patients with hydronephrosis, TREM1 was expressed on tubulointerstitial cells which was not detectable in renal biopsies from renal transplant patients with stable graft." (PMID 24358193, 2013). "In patients with hydronephrosis, TREM1 positive cells were observed in renal tissue." (PMID 24358193, 2013). "TREM1 expression has never been reported in human kidney disease and could contribute in inflammatory processes during hydronephrosis." (PMID 24358193, 2013).
Hyperglycemia (1 paper, 2022). An increased concentration of glucose in the blood. "However, hyperglycemia was reduced and shortened in TREM-1 KO mice as compared to WT littermates." (PMID 36699032, 2022).
hyperlipidemia (1 paper, 2013). "Although we observed an inhibited innate immune response and TREM-1 expression in hyperlipidemic ApoE−/− mice, the possible mechanism by which hyperlipidemia influences PRRs has not been fully understood." (PMID 23977160, 2013). "In our study, macrophages from ApoE−/− mice showed inhibited transcription of TLR2, TREM-1, TREM-3, and CD14 in quiescent state, whereas only TREM-1 expression was influenced by hyperlipidemia in bacteria stimulated macrophages." (PMID 23977160, 2013).
Hypothermia (1 paper, 2014). Reduced body temperature due to failed thermoregulation. "Hypothermia and body weight loss, which are characteristically associated with experimental influenza virus infection, were observed in Trem1+/+ mice at 7 days post infection." (PMID 24453980, 2014).
infarction (1 paper, 2022). A localised pathological necrosis of tissue resulting from obstruction of the blood supply usually by a thrombus, an embolus, or vascular torsion. "In AMI models, TREM-1 is upregulated in the infarction zone, and inhibiting TREM-1 could effectively alleviate myocardial inflammation and improve heart function." (PMID 35637975, 2022).
intervertebral disc degeneration (1 paper, 2022). "In conclusion, Circular RNA hsa_circ_0083756 promotes intervertebral disc degeneration by sponging miR‐558 and regulating TREM1 expression." (PMID 35187741, 2022).
intestinal inflammation (1 paper, 2014). "In particular, we were interested in the potential modulatory effect of TREM-1 ligation on neutrophil survival as delayed neutrophil apoptosis could also represent a critical pathogenic factor in intestinal inflammation." (PMID 24453980, 2014).
juvenile idiopathic arthritis (1 paper, 2020). Juvenile idiopathic arthritis (JIA) is the term used to describe a group of inflammatory articular disorders of unknown cause that begin before the age of 16 and last over 6 weeks. "This prediction has been partially confirmed in a previous work demonstrating that TREM1 was expressed on mature dendritic cells infiltrating the inflamed hypoxic joints of children affected with juvenile idiopathic arthritis." (PMID 32765489, 2020).
kidney injury (1 paper, 2024). Trauma to the kidney. "As an amplifier of inflammation, Trem1 has been shown to have a role in cIgA1-induced kidney injury and in maintaining tubular homeostasis through regulation of mitochondrial metabolic flexibility." (PMID 39529886, 2024).
leprosy (1 paper, 2023). Leprosy is a chronic infectious disease affecting primarily the skin and peripheral nervous system. "Concerning the genetic polymorphism analysis, associations between the genotypes CC+CT for TREM-1 rs2234246 and leprosy per se or the occurrence of leprosy were observed." (PMID 37457576, 2023). "Altogether, our findings suggest that the TREM-1 SNP may affect the risk of leprosy occurrence, making this an important candidate gene for future studies in more powerful genetic studies." (PMID 37457576, 2023). "There was a higher frequency of CC+CT genotypes of the TREM-1 rs2234246 than the TT genotype in leprosy patients (OR = 1.598; p = 0.04)." (PMID 37457576, 2023). "Frequency and distribution of TREM-1 rs2234246 in leprosy patients and the control group." (PMID 37457576, 2023).
leukoplakia (1 paper, 2025). A white patch or plaque on a mucous membrane that cannot be characterized clinically or pathologically as any other disease. "Compared to normal tissue, CD46 and TREM1 scores were significantly elevated in inflammatory, leukoplakia, and OSCC tissues (P < 0.05)." (PMID 41415031, 2025). "H-Score semi-quantitative analysis revealed that compared to normal tissue, both CD46 and TREM1 expression scores were significantly elevated in leukoplakia and OSCC tissues (P < 0.05), peaking in OSCC." (PMID 41415031, 2025). "In oral leukoplakia, CD46 expression is upregulated, membrane expression is enhanced in areas of abnormal epithelial hyperplasia, TREM1 expression is elevated, inflammatory cell infiltration is present, and LC3B/ATG5 expression is low." (PMID 41415031, 2025).
liver cirrhosis (1 paper, 2023). "Induction of CD14 + Trem-1 + iNOS + intestinal macrophages in liver cirrhosis patients released IL-6, NO, and accelerated intestinal permeability." (PMID 37273916, 2023).
lung diseases (1 paper, 2020). "The discovery of the eCIRP/TREM-1 interaction involved in the activation of ATII cells will support the development of novel therapeutic targets for ALI or other lung diseases." (PMID 32984356, 2020).
lupus nephritis (1 paper, 2016). Glomerulonephritis in the context of systemic lupus erythematosus. "Thus, TREM-1 blockade emerges as a potential therapeutic avenue for immune-mediated renal diseases such as lupus nephritis." (PMID 27083877, 2016).
Lyme disease (1 paper, 2016). Lyme disease (named after the towns in the USA where the disease was first identified) is a bacterial infection caused by Borrelia burgdorferi. "The prominent TREM1 signaling in acute Lyme disease observed here is consistent with previously published in vitro gene expression data of B. burgdorferi infection of human neural and primary monkey glial cell lines." (PMID 26873097, 2016).